ANO1 (anoctamin 1)
Diseases named in the same sentence as ANO1 in open-access papers (continued):
Sharing a sentence is not in itself a finding about the gene and the disease.
cancer (continued). "Neither treatment with MG132 nor with Chloroquine showed an effect on the ANO1-knockdown induced reduction of EGFR-protein levels, indicating that ANO1 does not affect the general turnover of EGFR in cancer cells." (PMID 25823819, 2015). "Especially, it induces MAPK and contributes directly to cancer progression, whereas ANO9 could inhibit the activity of ANO1 and other anoctamins, which implied that ANO9 might inhibit malignant progression." (PMID 26317553, 2015). "Although the reason for high expression of ANO1 in tumors is unclear, several studies have shown that ANO1 is involved in oncogenic signaling by activating EGFR and CAMK pathways to promote cell cycle and cancer progression." (PMID 26305547, 2015). "Overexpression and amplification of ANO1 in cancer had been described long before its molecular identity and function was discovered, resulting in multiple nomenclatures for ANO1 (also known as TMEM16A, DOG1, ORAOV2, and TAOS2)." (PMID 24599954, 2014). "Although no one knows why ANO1 is amplified in tumorigenesis and how it influences cancer cell proliferation, several recent studies have provided clues to crack the mysteries 7,9." (PMID 24639373, 2014). "We show that inhibition of ANO1 function is not sufficient to diminish proliferation of ANO1-dependent cancer cells." (PMID 24599954, 2014). "Since FLJ10261 (ANO1) was characterized using bioinformatics as a gene residing between FGF3 and FADD genes at 11q13 28, the genes including ANO1 amplified in the 11q13 core region were considered as markers of cancers." (PMID 24639373, 2014). "Overall, there is no strong evidence as yet to interpret how an activated ANO1 affects cancer cell proliferation and migration." (PMID 24639373, 2014). "Although the ANO1 gene is located on the 11q13 locus, a region which is known to be amplified in different types of human carcinomas, a detailed analysis of Ano1 amplification and expression in HNSCC has not been performed." (PMID 22912841, 2012). "Moreover, Eact (an ANO1 functional activator) did not reduce ANO1 protein levels in either cancer cell line." (PMID 40520165, 2025). "High ANO1 expression also reprograms cholesterol metabolism by inhibiting LXR-mediated cholesterol efflux, leading to intracellular cholesterol accumulation, which enhances cancer cell survival, increases metastatic potential, and is linked to resistance to anti-PD-1 therapy." (PMID 40356890, 2025). "Interestingly, the suppressed expression and secretion of TGF-β resulting from ANO1 knockdown were reversed by the ferroptosis inhibitor Fer-1, highlighting a potential opposite relationship between ferroptosis and TGF-β release within cancer cells." (PMID 38649701, 2024). "On the other hand, although several inhibitors targeting ANO1 has been developed, their potential effectiveness against cancer remain unexplored yet by clinical trials because of the lack of strong preclinical evidence supporting ANO1's value as a promising therapeutic target in cancer." (PMID 37341301, 2023). "More recently, several ANO1 inhibitors, including CaCCinh-A01, T16Ainh-A01, tannic acid, idebenone, benzbromarone, and Ani9 have been identified through high-throughput screening (HTS) of compound libraries and were found to inhibit the proliferation of cancer cells." (PMID 33172169, 2020). "In addition, the expression of ANO1 was not involved in the proliferation of cancer cells or the survival of cancer patients." (PMID 29416639, 2018). "In addition, although there is no definitive report regarding the role of ANO1 in the stemness of cancer cells, it is suspected based upon the result that ANO1 induced expression of MYC." (PMID 29416639, 2018). "However, it is reported that inhibition of ANO1 activity alone is not sufficient to inhibit cancer cell proliferation, suggesting a novel function of ANO1 protein in cancer." (PMID 29899325, 2018).
cancer (continued). "However, contrary reports also show that inhibition of ANO1 function alone is not sufficient to diminish proliferation of ANO1-dependent cancer cells." (PMID 27732935, 2016). "In addition to the role of ANO1 in cell-cycle progression and proliferation, ANO1 has recently been shown to be involved in oncogenic signaling by activating EGFR and CAMK pathways to promote cancer progression, and enhancing MAPK signaling for progression of cell cycle." (PMID 26305547, 2015). "ANO1‐negative cases possessed longer irPFS/irOS than ANO1‐positive cases, which retained either in GC (with statistical significance/tendency for irPFS/irOS) or nonGC (EC+CRC+other cancers, with statistical tendency)." (PMID 37341301, 2023). "Hence, ANO1 may be considered an important target for the treatment of various cancers; however, its role in NSCLC has not been fully elucidated, nor have anticancer drug candidates capable of inhibiting ANO1 been identified." (PMID 34281152, 2021).
infection (7 papers, 2015 to 2024). The state of being infected such as from the introduction of a foreign agent such as serum, vaccine, antigenic substance or organism. "A shift in the expression of antimicrobial genes and proinflammatory modules in Ano1 mutants indicates that these mutants may be more prone to infection and inflammation, which result in secondary pulmonary dysplasia." (PMID 32286221, 2020). "Surface biotinylation assay with U251 cells also showed that infection with adenovirus containing 14-3-3γ shRNA-1 caused a significant reduction in the surface expression of ANO1 compared with adenovirus containing Sc shRNA, without affecting total ANO1 protein levels." (PMID 27212225, 2016). "Accordingly, we knocked down ANO1 in LNCap, DU145 and PC3 cells using a lentiviral shRNA infection system which allows a prolonged depletion for ANO1 and thus our study under identical conditions." (PMID 38773164, 2024).
kidney disease (2 papers, 2022 to 2023). "The Cl−-transporting proteins CFTR, SLC26A9, and anoctamin (ANO1; ANO6) appear to have more in common than initially suspected, as they all participate in the pathogenic process and clinical outcomes of airway and renal diseases." (PMID 37686084, 2023).
gastrointestinal disorders (1 paper, 2024). "2021–2023: the primary emphasis during this period was on functional gastrointestinal disorders, the investigation of ANO1, and the interactions between ICC and enteric neurons." (PMID 38831987, 2024).
heart diseases (1 paper, 2025). "Overexpression of ANO1 enhances depolarisation, increases the potential for Ca2+ channel opening, vasoconstriction, and ultimately decreases coronary perfusion, which can lead to ischaemic heart disease." (PMID 41210337, 2025).
peripheral neuropathy (1 paper, 2015). A disorder affecting the peripheral nervous system. "Recent evidence suggests that sensory neuronal ANO1 Cl− channels are involved in hyperalgesia and allodynia from tissue inflammation and peripheral neuropathy." (PMID 26364309, 2015).
ANO1 also shares sentences with these, for which no sentence is quoted: schwannoma (19 papers); pulmonary hypertension (18); mesenchymal tumors (17); leiomyoma (14); adenocarcinoma (9); acinic cell carcinoma (8); pancreatic ductal adenocarcinoma (8); respiratory diseases (8); gastrointestinal tumors (7); salivary gland tumors (7); synovial sarcoma (6); angiosarcoma (5); gastric adenocarcinoma (5); spindle cell tumors (5); inflammatory myofibroblastic tumor (4); invasive breast carcinoma (4); lung disease (4); malignant peripheral nerve sheath tumor (4); neuroendocrine tumors (4); adenoid cystic carcinoma (3); cardiovascular disease (3); chondroblastoma (3); chronic kidney disease (3); ductal adenocarcinomas (3); lymphoma (3); neurofibroma (3); nonalcoholic fatty liver disease (3); renal fibrosis (3); type 2 diabetes (3); adenosis (2).
A further 162 diseases each share a sentence with ANO1 in 2 papers or fewer.